RNU6-152P (RNA, U6 small nuclear 152, pseudogene)
Gene: Small nuclear RNA gene on chromosome 1 (182,327,068 to 182,327,174, forward strand). Ensembl gene ENSG00000206764.
Homologues: Orthologues: chimpanzee U6 (99% identical), macaque U6 (87% identical), rabbit U6 (80% identical), mouse Gm56000 (72% identical), guinea pig U6 (66% identical), pig U6 (66% identical). Paralogues in human: RNU6-21P (87% identical), RNU6-33P (86% identical), RNU6-1 (85% identical), RNU6-1026P (85% identical), RNU6-15P (85% identical), RNU6-2 (85% identical), RNU6-3P (85% identical), RNU6-4P (85% identical), RNU6-5P (85% identical), RNU6-6P (85% identical), RNU6-9 (85% identical), RNU6-11P (84% identical), and 1289 more.